FGF2 (fibroblast growth factor 2)
Diseases named in the same sentence as FGF2 in open-access papers (continued):
Sharing a sentence is not in itself a finding about the gene and the disease.
Ewing sarcoma (9 papers, 2005 to 2022). A small round cell tumor that lacks morphologic, immunohistochemical, and electron microscopic evidence of neuroectodermal differentiation. "However, adhesion combined with serum had a strong synergistic effect and caused Ewing tumour cell resistance to FGF2-induced cell death." (PMID 15685229, 2005). "The obtained data confirm and extend recent findings showing that Ewing tumour cells express FGF2 and its receptors and that extracellularly supplied FGF2 induces apoptosis." (PMID 15685229, 2005). "While in vitro studies had shown that fibroblast growth factor 2 (FGF2) can induce cell death in Ewing tumours, it remained unclear how Ewing tumour cells survive in vivo within a FGF2-rich microenvironment." (PMID 15685229, 2005). "We were able to confirm that FGF2 has a dose-dependent growth-inhibitory effect on most Ewing tumour cell lines in vitro and that this growth inhibition is associated with induction of apoptosis." (PMID 15685229, 2005). "In order to identify the receptor(s) that transduces the inhibitory FGF2 signal in Ewing tumour cells, Western blot analyses identified FGFR1, -2 protein in all cell lines, whereas FGFR-3 protein was only detected in TC-71, VH-64 and WE-68." (PMID 15685229, 2005). "In a panel of Ewing tumour cell lines, either adhesion to collagen or exposure to serum alone only had a minor protective effect against FGF2." (PMID 15685229, 2005). "Nearly 15 years ago, Schweigerer and co-workers isolated FGF2 from Ewing tumour cells." (PMID 15685229, 2005). "These latter conditions most likely best reflect the microenvironment of human Ewing tumours in vivo, suggesting that FGF2-induced apoptosis may be a tissue culture artefact." (PMID 15685229, 2005). "However, the biological and clinical impact of expression of FGF2 and its receptors by Ewing tumour cells remains obscure." (PMID 15685229, 2005). "Expression of FGF2 was assessed in a panel of Ewing tumour cell lines." (PMID 15685229, 2005). "Recently, it has been found out that FGF2-induced activation of JNK may play a crucial role in inducing apoptosis in Ewing sarcoma-related Askin tumour cells." (PMID 15685229, 2005). "Exposure to serum alone (in the presence of 15% foetal calf serum) or integrin-mediated adhesion (serum-free monolayer cultures on a collagen matrix), both rendered one of the four Ewing tumour cell lines at least partially resistant to 5 ng ml−1 FGF-2 (serum in RD-ES and adhesion in RM-82)." (PMID 15685229, 2005). "If this hypothesis is true, a caspase 8 inhibitor would be expected to protect Ewing tumour cells from FGF2-induced apoptosis." (PMID 15685229, 2005). "In conclusion, although the biological function of FGF2 expression remains to be defined, several mechanisms could be identified by which Ewing tumour cells escape the detrimental effects of FGF2." (PMID 15685229, 2005). "Although it could be demonstrated that Ewing tumour cells escape FGF2-induced apoptosis through microenvironment-mediated survival signals, the biological function of FGF2 expression in Ewing tumour cells remains unknown." (PMID 15685229, 2005). "Nevertheless, four out of six Ewing tumour cell lines in vitro die after exposure to FGF2." (PMID 15685229, 2005). "Thus, Ewing tumour cells escape FGF2-induced cell death by modulating FGF2 signalling." (PMID 15685229, 2005). "Moreover, in a panel of human Ewing's sarcoma family tumor cells, sublethal concentrations of bortezomib (proteasome inhibitor) or VE‐821 (ATR inhibitor) induced cell death when combined with FGF2." (PMID 30422399, 2019). "However, lack of secretion of FGF2 by Ewing tumour cells is insufficient to explain formation, survival and metastasis of these tumour cells in or to the bone marrow microenvironment, which is a rich source of FGF2." (PMID 15685229, 2005).
Ewing sarcoma (continued). "The lack of secretion of FGF2 under standard culture conditions may be one of the mechanisms by which Ewing tumour cells protect themselves from autocrine growth inhibition and induction of apopotosis." (PMID 15685229, 2005). "In contrast to L87/4 stroma cells, however, no FGF2 could be detected in the culture medium of the Ewing tumour cell lines." (PMID 15685229, 2005). "However, IGF1 at 0.2–20 ng ml−1 neither increased the colony-forming ability and proliferative activity of Ewing tumour cells under serum-free conditions, nor was IGF1 sufficient to protect TC-71 cells from FGF2-induced apoptosis (data not shown)." (PMID 15685229, 2005).
ischemic disease (9 papers, 2010 to 2022). Lack of blood supply to an area of the body, resulting in impairment of tissue oxygenation. "In previous studies, MSC transplantation has been performed in the field of ischemic diseases, and it has been suggested that its plausible effects would be mediated largely through paracrine actions of locally released arteriogenic cytokines including FGF2 and VEGF." (PMID 25977928, 2015).
medulloblastoma (9 papers, 2010 to 2024). A malignant, invasive embryonal neoplasm arising from the cerebellum. "We observed that overall growth factor production was low in medulloblastoma cell lines, except for FGF-2." (PMID 26496080, 2015). "Whereas VEGF-A, PDGF-AB, FGF-2 and EGF show weak bypassing potential in addition to either crizotinib or canertinib, addition of HGF shows strong bypassing potential by significantly bypassing the growth-inhibitory effects of canertinib in medulloblastoma cells." (PMID 26496080, 2015).
Oral ulcer (9 papers, 2016 to 2024). Erosion of the mucous mebrane of the mouth with local excavation of the surface, resulting from the sloughing of inflammatory necrotic tissue. "This investigation reveals that the topical application of AdMSCM oral gel is able to enhance the clinical outcome, angiogenesis, and expression of VEGFA and FGF-2 in the oral ulcer animal model (R. novergicus)." (PMID 36963426, 2024). "Ren & Shun (2002) conducted a double-blind study, in which 121 patients with mild aphthous ulcers (mouth ulcers) were randomly assigned to either a FGF2 group (n = 63) or a control group (n = 58)." (PMID 26793421, 2016). "This study will confirm whether the application of AdMSCM oral gel can enhance the expression of VEGFA and FGF-2, angiogenesis, and clinical outcome in oral ulcer rat models." (PMID 36963426, 2024). "This study will analyze the clinical outcome, angiogenesis, and expression of FGF-2 and VEGFA in the oral ulcer rat model after AdMSCM oral gel application." (PMID 36963426, 2024). "Several therapeutic applications for FGF-2 have been identified in the literature, with the efficacy of FGF-2 for the treatment of a wide variety of conditions, such as burns, mouth ulcers, fractures, pressure and diabetic ulcers and critical limb ischemia evaluated in various clinical trials." (PMID 34834177, 2021).
bipolar disorder (8 papers, 2017 to 2024). A disorder of the brain that causes unusual shifts in mood, energy, activity levels and the ability to carry out day-to-day tasks. "As for bipolar disorder, serum levels of FGF2 are higher in patients with manic episode than those in healthy controls." (PMID 30804785, 2019). "However, further studies are required to reveal the relationship between FGF-2 and bipolar disorder." (PMID 32283906, 2020). "FGF2 is related to bipolar disorder at the genetic level of humans." (PMID 30804785, 2019). "The NGF, FGF2, NT-3, BDNF, IL-1-β, and dopamine factors also indirectly impact the action of GSK-3β in bipolar disorder." (PMID 37569304, 2023). "Factors such as fibroblast growth factor (FGF)-2, vascular endothelial growth factor (VEGF), nerve growth factor (NGF), and insulin-like growth factor (IGF)-1 might be potential candidate biomarkers for bipolar disorder." (PMID 31118905, 2019). "In a postmortem study, it was found that FGF-2 and FGFR1 levels did not change in the brain in bipolar disorder patients." (PMID 32283906, 2020).
endometrial cancer (8 papers, 2002 to 2024). Primary or metastatic malignant neoplasm involving the endometrium (mucous membrane that lines the endometrial cavity). "In the same line of evidence, Sef impairs FGF2-induced MAPK/ERK signaling activation in endometrial cancer cells, thus inhibiting their growth and proliferation." (PMID 35805075, 2022). "The microvessel density in FGF2-overexpressing endometrial cancer xenografts was reduced to control levels by [NSIS6S]-[NSIS]5 with inhibition of FGF2 signaling in tumor blood vessels." (PMID 27490176, 2016). "Pathologic disruption of mRNA co-expression patterns supports the notion of a cross talk between IGF1, EGF, and FGF2 signaling pathways in the promotion of endothelial cell proliferation and differentiation of endometrial cancer." (PMID 24904527, 2014). "As demonstrated, molecules secreted by CAFs, i.e., TGFβ1, EGF, HGF, and FGF-2, potentiate the migration and invasion of endometrial cancer cells (RL-952) when administered exogenously, thus inducing lung metastasis in vivo in mouse subcutaneous xenograft assay." (PMID 34501347, 2021). "Insulin-like growth factor-1 and epidermal growth factor (EGF) downregulation and fibroblast growth factor-2 (FGF2) up-regulation seem to constitute key features of endometrial cancer progression, as demonstrated in a collection of 30 cancer specimens that were compared to normal adjacent tissue." (PMID 24904527, 2014). "The main cytokines secreted by CAFs isolated from human endometrial cancer tissue include MCP-1, CCL5, RANTES, interleukin-6, and -8 (IL-6, IL-8) VEGF, EGF, HGF, FGF-2, as well as TGFβ1 isoform." (PMID 34501347, 2021). "In addition, Sef expression is stimulated by FGF2-induced MAPK/ERK signaling, thus indicating the existence of a Sef-mediated negative feedback loop that regulates FGF cascade in endometrial cancer cells." (PMID 35805075, 2022).
head and neck squamous cell carcinoma (8 papers, 2010 to 2022). A squamous cell carcinoma that arises from any of the following anatomic sites: lip and oral cavity, nasal cavity, paranasal sinuses, pharynx, larynx, and salivary glands. "ERK upregulation caused by increasing FGFR3 level in HNSCC (head and neck squamous cell carcinoma) cells led to an increase in FGF2 expression, which correlated with reduced sensitivity to bevacizumab." (PMID 34830951, 2021). "The specificity of this ligand is reflected by the observation that the growth rate of head and neck squamous cell carcinoma cells expressing abundant FGF2 is significantly inhibited upon treatment with FP-1039, whereas HNSCC cells that express little FGF2 is not affected." (PMID 23900974, 2013). "Moreover, Marshallet al. showed that FGFR2 and FGFR3 are commonly expressed in head and neck squamous cell carcinoma (HNSCC) cells and are activated by autocrine FGF2." (PMID 36111743, 2022). "Importantly, FGF2 is overexpressed in both human head and neck squamous cell carcinoma (HNSCC) and VECs, promoting tumor vascularization." (PMID 33167307, 2020).
mood disorder (8 papers, 2015 to 2026). A cognitive disorder a disturbance in which the person's mood is hypothesized to be the main underlying feature. "This is especially notable given the relatively high brain expression of FGF2 among individuals with mood disorders." (PMID 35706690, 2022). "Levels of hippocampal FGF2 and FGF2 receptors are decreased in post-mortem brains of individuals with mood disorders." (PMID 30273396, 2018). "In addition, previous studies have shown that FGF2 can act as an anxiolytic and anti-depressive agent in rodents and that decreased levels of hippocampal FGF2 and FGF2 receptors have been found in postmortem brains of individuals with mood disorders." (PMID 37108630, 2023). "In humans, FGF2 and FGF receptor levels are downregulated in post-mortem tissue of individuals that had a history of mood disorders." (PMID 30273396, 2018). "No changes in FGF2 were noted in the post-mortem brains of individuals with mood disorders that were successfully treated with anti-depressant medication prior to death." (PMID 30273396, 2018). "For instance, FGF1, FGF2, FGF receptor (FGFR) 2 and FGFR3 were significantly down-regulated in the frontal cortex of MDD patients, which strongly suggests that FGF signaling must be disrupted in mood disorders." (PMID 26537115, 2015). "Specifically, FGF1, FGF2, FGF receptor (FGFR) 2 and FGFR3 were down-regulated in the frontal cortex of MDD patients, which strongly suggests that FGF signaling must be disrupted in mood disorders." (PMID 26537115, 2015). "Furthermore, no changes in FGF2 were noted in the post-mortem brains of individuals with mood disorders that were successfully treated with anti-depressant medication prior to death." (PMID 30273396, 2018). "The effect of FGF9 was found to be opposite that of FGF2, which may be due to the inverse relationship between FGF9 expression and FGF2 expression, and FGF2 and FGF9 may act as physiological antagonists to mediate emotionality and vulnerability in mood disorders." (PMID 32184729, 2020).
ovarian tumor (8 papers, 2007 to 2024). "Ovarian tumors study showed patients with high cytoplasmic FGF2 were associated with reduced tumor aggressiveness and increased survival rates compared with patients with low expression of FGF2." (PMID 25890121, 2015). "Ovarian tumors with high cytoplasmic FGF2 are associated with reduced tumor aggressiveness and increased survival rates compared with patients with low levels of FGF2." (PMID 23554977, 2013). "Reduction of non-FGF2-dependent ovarian tumor growth occurred when [NSIS6S]-[NSIS]5 was combined with cisplatin." (PMID 27490176, 2016). "We previously showed that all cellular elements in ovarian tumour tissue synthesised HS but biologically active HS (i.e. HS capable of binding FGF2 and its receptor) was confined to ovarian tumour endothelium." (PMID 17437011, 2007). "In a previous study, we showed that in ovarian tumours the distribution of biologically active HS revealed by the colocalisation of FGF2 and the FGF-receptor probe (FR1c-AP) was confined to the tumour endothelium." (PMID 17437011, 2007). "However, the role of FGF2 in ovarian tumor progression remains to be elucidated." (PMID 23554977, 2013).
psoriasis (8 papers, 2017 to 2025). An autoimmune condition characterized by red, well-delineated plaques with silvery scales that are usually on the extensor surfaces and scalp. "However, Acitretin used in psoriasis, Niclosamide used for treating tapeworm infection, and Sirolimus used in organ rejection or lymphangioleiomyomatosis treatment can be repurposed against FGF2." (PMID 35456223, 2022).
spinal cord injury (8 papers, 2017 to 2025). Penetrating and non-penetrating injuries to the spinal cord resulting from traumatic external forces (e.g., WOUNDS, GUNSHOT; WHIPLASH INJURIES; etc.). "In the treatment of spinal cord injury (SCI), basic fibroblast growth factor (bFGF or FGF-2) is a notable example of a growth factor that activates endogenous stem cells to promote therapeutic effects." (PMID 41291782, 2025).
triple-negative breast carcinoma (8 papers, 2014 to 2025). An invasive breast carcinoma which is negative for expression of estrogen receptor (ER), progesterone receptor (PR), and human epidermal growth factor receptor 2 (HER2). "High FGF2 expression and secretion have been found in triple-negative breast cancer cell lines, in particular in those showing a mesenchymal phenotype." (PMID 30866584, 2019). "Previously published studies have demonstrated increased production of FGF-2 as a mechanism for enhanced FGFR activity in triple negative breast cancers." (PMID 26215578, 2015). "The proliferation of triple-negative breast cancer cells is stimulated by Fgf2 through an autocrine loop." (PMID 24658335, 2014). "The selected HS-binding peptide interacts with a specific structure of heparan sulfate and inhibits tumor growth of triple-negative breast cancer cells, possibly interfering with the proliferation signaling modulated by FGF-2 and consequently decreasing angiogenesis." (PMID 34422650, 2021). "To explore the FGF2 expression pattern in estrogen receptor positive (ER + ) and aggressive triple negative breast cancer (TNBC) subtypes, we performed immunohistochemical staining for FGF2 in 38 ER+ and 18 TNBC primary tumor samples." (PMID 40425576, 2025).
brain injury (7 papers, 2013 to 2025). Acute and chronic (see also brain INJURIES, CHRONIC) injuries to the brain, including the cerebral hemispheres, CEREBELLUM, and brain STEM. "In conclusion, EE enhances endogenous angiogenesis and neurobehavioral functions mediated by upregulation of FGF-2 in chronic hypoxic-ischemic brain injury." (PMID 24098645, 2013). "The upregulation of FGF-2 induced by EE promoted functional recovery through enhanced angiogenesis in an animal model of chronic HI brain injury." (PMID 24098645, 2013). "Animals that exercise after brain injury show an increase in the expression of neurotrophic factors, such as BDNF, HGF, and FGF-2, which regulate neuronal survival and differentiation, synaptic plasticity, as well as angiogenesis in the brain." (PMID 24098645, 2013). "In addition, FGF2 overexpression by bioengineered hESCs may facilitate neuronal repair, since several experimental studies in the CNS and PNS have revealed that this growth factor plays an important role in neuronal axonal regeneration and repair after brain injuries and spinal cord injuries." (PMID 33178285, 2020).
Cirrhosis (7 papers, 2012 to 2025). A chronic disorder of the liver in which liver tissue becomes scarred and is partially replaced by regenerative nodules and fibrotic tissue resulting in loss of liver function. "It has been shown previously by different groups that serum levels of FGF2 are elevated in cirrhosis and HCC patients." (PMID 37770545, 2023). "Hepatitis and cirrhosis groups showed positive FGF-2 expression as granular cytoplasmic staining in periportal, perivenular and intermediate hepatocytes as well as bile ductular epithelial cells." (PMID 22839096, 2012). "In hepatitis and cirrhosis cases, positive correlations were detected between FGF-2 and CK19 positivity (r = 0.703, p = 0.002 and r = 0.536, p = 0.048, respectively)." (PMID 22839096, 2012). "TGF-β is anti-inflammatory and involved in inhibiting apoptosis, while TNF-α, IL-8, FGF2, and VEGFA are involved in hepatic injury or cirrhosis through cell proliferative and angiogenic activities." (PMID 41219858, 2025).